RAB25 (RAB25, member RAS oncogene family)
Description:
The small GTPases Rab are key regulators of intracellular membrane trafficking, from the formation of transport vesicles to their fusion with membranes. Rabs cycle between an inactive GDP-bound form and an active GTP-bound form that is able to recruit to membranes different set of downstream effectors directly responsible for vesicle formation, movement, tethering and fusion (By similarity). RAB25 regulates epithelial cell differentiation, proliferation and survival, thereby playing key roles in tumorigenesis. Promotes invasive migration of cells in which it functions to localize and maintain integrin alpha-V/beta-1 at the tips of extending pseudopodia. Involved in the regulation of epithelial morphogenesis through the control of CLDN4 expression and localization at tight junctions (By similarity). May selectively regulate the apical recycling pathway (By similarity). Together with MYO5B regulates transcytosis (By similarity).
Synonyms: CATX-8; RAB11C
Tractability: Small molecule: a structure with a bound ligand is known. Antibody: UniProt places it where antibodies can reach, with high confidence; its Gene Ontology location is reachable by antibodies, with high confidence; the Human Protein Atlas places it where antibodies can reach. PROTAC: ubiquitination databases record sites on it.
Gene: Protein-coding gene on chromosome 1 (156,061,148 to 156,070,514, forward strand). Ensembl gene ENSG00000132698.
Subcellular location: Cell membrane; Cytoplasmic vesicle; Cell projection, pseudopodium membrane
Subcellular location (Human Protein Atlas): Plasma membrane
Pathways (Reactome):
Metabolism of proteins: RAB geranylgeranylation
Gene Ontology:
Molecular function: G protein activity; myosin V binding; protein binding; GTPase activity; GTP binding
Biological process: positive regulation of cell population proliferation; positive regulation of epithelial cell migration; pseudopodium organization; regulation of vesicle-mediated transport; epithelial cell morphogenesis; exocytosis
Cellular component: cytoplasmic vesicle; extracellular exosome; plasma membrane; pseudopodium; Golgi apparatus; recycling endosome; pseudopodium membrane
Genetic constraint (gnomAD): Loss-of-function variants: 23 observed, 26 expected, observed/expected ratio (o/e) 0.88, 90% interval 0.64 to 1.25. The upper end of that interval is the gene's LOEUF score, 1.25, which puts it in group 5 of 6, group 1 being the genes least tolerant of losing a copy. Missense variants: 244 observed, 287.4 expected, observed/expected ratio (o/e) 0.85, 90% interval 0.76 to 0.94. Synonymous variants: 102 observed, 115.88 expected, observed/expected ratio (o/e) 0.88, 90% interval 0.75 to 1.04.
Homologues: Orthologues: chimpanzee RAB25 (100% identical), macaque RAB25 (100% identical), pig RAB25 (98% identical), rat Rab25 (97% identical), dog RAB25 (96% identical), mouse Rab25 (96% identical), guinea pig RAB25 (94% identical), rabbit RAB25 (73% identical), zebrafish rab25b (70% identical), zebrafish rab25a (67% identical), tropical clawed frog rab25 (65% identical). Paralogues in human: RAB11A (60% identical), RAB11B (59% identical), RAB4B (41% identical), RAB43 (40% identical), RAB4A (40% identical), RAB14 (40% identical), RAB2B (39% identical), RAB5A (39% identical), RAB5C (39% identical), RAB1B (38% identical), RAB2A (38% identical), RAB30 (38% identical), and 56 more.
Diseases named in the same sentence as RAB25 in open-access papers:
RAB25 is named in the same sentence as 57 diseases in open-access papers, as found by Europe PMC text mining. Sharing a sentence is not in itself a finding about the gene and the disease. The quoted sentences say what the papers report.
ovarian carcinoma (39 papers, 2008 to 2025). A malignant neoplasm originating from the surface ovarian epithelium. "Rab25, a small GTPase of the Rab11 subfamily, has been functionally linked to the progression and aggressiveness of ovarian cancer." (PMID 29482638, 2018). "Overexpression of Rab25 has been implicated in poor prognosis in ovarian cancer, with stapled peptide inhibitors of Rab25-effector binding inhibiting migration and proliferation." (PMID 30217979, 2018). "Elevated expression of Rab25 was significantly associated with shorter survival time of patients with bladder cancer, advanced non-small cell lung cancer, ovarian cancer, breast cancer, clear cell renal cell carcinoma and prostate cancer." (PMID 28969096, 2017). "In the study of ovarian cancer TCGA data set, decrease in Rab25 promoter methylation was associated with increase in Rab25 mRNA level, suggesting the elevation of Rab25 level by epigenetic regulation." (PMID 28969096, 2017). "Based on these observations, we aimed to elucidate the role of HIF-1α in mediating the association between Rab25 expression and the aggressive and tumourigenic phenotype of ovarian cancer cells." (PMID 26967059, 2016). "High expression of Rab25 has been frequently associated with poor prognosis in breast and ovarian cancer." (PMID 27716280, 2016). "We have demonstrated that the Rab25 amplicon and Rab25 expression is associated with a worsened outcome in ovarian cancer and increased the aggressiveness of a subset of breast cancer cell lines." (PMID 27259233, 2016). "This study aimed to determine the role of HIF-1 in the invasive and metastatic ovarian cancer phenotype associated with expression of the small GTPase protein Rab25." (PMID 26967059, 2016). "The small GTPase Rab25 has been functionally linked to tumour progression and aggressiveness in ovarian cancer and promotes invasion in three-dimensional environments." (PMID 26967059, 2016). "Our data demonstrated that Rab25 expression to levels found in human tumors with RAB25 amplification, which is associated with aggressiveness of breast and ovarian cancer, increases OPG levels in the supernatant of cancer cells." (PMID 25520884, 2013). "Breast, bladder, and ovarian cancer studies have suggested that a high expression of RAB25 is associated with poor prognosis; however, these results are controversial." (PMID 24403269, 2013). "Amongst this group of genes, ITGA5 (up-regulated) encodes for the alpha 5 subunit of the alpha-5/beta-1 integrin that associates with RAB25 to promote invasive migration of ovarian carcinoma cells." (PMID 22724020, 2012). "It was therefore of interest in 2004 when Mills and colleagues noted that regions of chromosome 1 amplification associated with ovarian cancer were associated with marked increases in the expression of Rab25." (PMID 21063400, 2011). "Norman and colleagues have previously demonstrated that increases in Rab25 in ovarian cancer cells were associated with aberrations in the cell surface localisation of β1-integrin." (PMID 21063400, 2011). "Whereas Rab25 overexpression is associated with ovarian cancer aggressive behaviour, Rab25 expression is decreased in human colon cancers independent of stage." (PMID 21063400, 2011). "Rab35 was chosen as it was the most highly upregulated gene in the cDNA microarray experiment, and Rab25 was chosen as this protein has been linked with ovarian cancer." (PMID 19623182, 2009). "A high level of RAB25 protein in patients with either breast or ovarian cancer was associated with an almost 50% reduction in five year survival rates." (PMID 18822129, 2008). "Specifically, Rab25 mediates invasive migratory phenotypes by directing the localization of integrin-recycling vesicles to the plasma membrane via the association with α5β1 integrins, resulting in increased cell motility in A2780 human ovarian cancer cells." (PMID 31973201, 2020).
ovarian carcinoma (continued). "These genes include RAB25, a member of the RAS oncogene family, recently implicated in the regulation of cell proliferation and apoptosis in ovarian cancer cells and with reports that tumor cells overexpressing the RAB25 protein were more aggressive and associated with a poorer clinical outcome." (PMID 18822129, 2008). "The native matrix produced by CAFs, synergizing with an upregulation of the small GTPase Rab25 often present in ovarian cancer cells, triggered a robust increase in the secretion of ADAMTS5, driven by NF‐κB‐dependent transcriptional activation." (PMID 40406984, 2025). "We found that the small GTPase Rab25 promoted the expression of ADAMTS5 in ovarian cancer cells, through the activation of the NF‐κB signalling pathway." (PMID 40164572, 2025). "This study highlights the underappreciated influence of CAFs on cancer cell behavior and unveils a striking pathway in which CAF‐derived matrix selectively activates a Rab25–NF‐κB–ADAMTS5 axis in ovarian cancer cells." (PMID 40406984, 2025). "In contrast, Rab25 deficiency or administration with LY294002, significantly elevates the sensitivity of these ovarian cancer cells to cisplatin." (PMID 38695990, 2024). "Compared with the ES‐2 ovarian cancer cell line that is cisplatin‐sensitive, overexpression of Rab25 promotes PI3K/AKT signaling in SKOV‐3 ovarian cancer cells that are cisplatin‐resistant." (PMID 38695990, 2024). "Here, we used BioID-based proximity labelling to characterise the protein complexes that form around recycling vesicles in a mesenchymal, migratory, ovarian cancer cell line model, specifically focusing on Rab4a, Rab11a and Rab25." (PMID 37232246, 2023). "Depletion of Rab4 and Rab11, or expression of Rab25 at levels similar to those seen in aggressive ovarian cancer, had significant effects on the architecture of F-actin within protrusions of cells moving in the 3D CDM." (PMID 37232246, 2023). "A previous study showed that knockdown of RAB25 promotes autophagy and inhibits cell growth in ovarian cancer cells." (PMID 36923938, 2023). "Rab11a, Rab11b, and Rab25 were significantly enriched in ovarian cancer, both for primary and recurrent tumors." (PMID 35708998, 2022). "Dox-induced Rab25 expression levels in ‘low’ sorted cells were comparable to endogenous Rab25 expression levels in OVCAR-3 ovarian cancer cell lines over 48 hr and Rab25 expression levels correlated with Tet-On 3G levels as expected." (PMID 35708998, 2022). "To demonstrate the potency of our strategies on closely related genes, we deployed them to study members of the Rab11 family (Rab11a, Rab11b, and Rab25) in an ovarian cancer cell line that lacks endogenous Rab25 expression." (PMID 35708998, 2022). "By contrast, Rab25 promotes integrin β1 trafficking to the cytoplasmic membrane in non-small-cell lung cancer and ovarian cancer and acts as a tumor promoter." (PMID 34141705, 2021). "In ovarian cancer, Rab25-medicated integrin β1 activates EGFR/VEGF/Snail axis and then promote cell invasion." (PMID 34141705, 2021). "A2780 ovarian carcinoma cells that stably express Rab25 are an accurate model of an aggressive tumor, and Rab25 increases invasion in a 3D microenvironment." (PMID 34287617, 2021). "Rab25 increases glycogen reserve and ATP levels in ovarian cancer cells through regulating the transport of GLUT1 to the cell surface and thus enhancing glucose uptake." (PMID 34141705, 2021). "For example, in ovarian cancer cells, Rab25 knockdown increases autophagy levels and induces apoptosis." (PMID 34141705, 2021). "Rab25 is another Rab frequently amplified in cancer contributing to the progression of breast and ovarian cancer." (PMID 31973201, 2020). "The tumorigenic role of RAB25 is reported in non-small cell lung cancer, gastric cancer, and ovarian cancer, whereas some report its tumor suppressor function in breast and colon cancers." (PMID 32759795, 2020).
ovarian carcinoma (continued). "Rab25, a small GTPase, has been considered as an oncogene in several types of malignancies, including ovarian cancer, via inducing cell proliferation and suppressing apoptosis/anoikis." (PMID 30791431, 2019). "RAB25 is related to the proliferation, survival, migration and invasion of ovarian cancer cell according to the literature and human gene database." (PMID 30944378, 2019). "Enhanced Rab25 expression in ovarian cancer cell lines results in increased cell proliferation, inhibition of apoptosis and anoikis, as well as increased aggressiveness in vivo, which has been found to rely on the activation of HIF-1." (PMID 29482638, 2018). "Analysis of 21 epithelial ovarian cancers showed a direct relationship between copy number and expression of Rab25, indicating mRNA overexpression of Rab25 is likely due to amplification of RAB25 gene." (PMID 28969096, 2017). "When Rab25 acts as an oncogene, Rab25 enhances α5β1 integrin recycling to the plasma membrane, leading to increase in cancer progression of ovarian cancer." (PMID 28969096, 2017). "Knockdown of Rab25 was reported to increase apoptosis in ovarian cancer cells and tobacco carcinogen-induced lung cancer model." (PMID 28969096, 2017). "In ovarian cancer cells, knockdown of Rab25 increases the conversion of LC3-I to LC3-II, a critical step for autophagy, and induces apoptosis." (PMID 27716280, 2016). "Enforced Rab25 expression in ovarian cancer cell lines results in increased cell proliferation, inhibition of apoptosis and anoikis and increased aggressiveness in vivo." (PMID 26967059, 2016). "Increased glycogen accumulation in Rab25-expressing cells has been observed both in vitro and in vivo in ovarian cancer patient tumour samples." (PMID 26967059, 2016). "We identified this candidate gene (Rab25) in the altered regions (gain on chromosome 1q) of endometrial and ovarian cancers." (PMID 27876019, 2016). "Rab25 expression is upregulated in around 80% of ovarian cancer samples compared to normal ovarian epithelium, and increased Rab25 expression correlates with increasing tumour stage." (PMID 26967059, 2016). "RAB25 has been observed to be upregulated in prostate and ovarian cancer, and is correlated with poor prognosis." (PMID 25351113, 2015). "Here, we show a modest increased cisplatin resistance induced by Rab25 expression in the ovarian cancer cell line A2780 in vitro." (PMID 26384969, 2015). "Over expression of Rab25 in ovarian cancer cell lines enhances anchorage-independent colony-formation, cell proliferation and cell survival over various stress conditions." (PMID 25815277, 2015). "Forced expression of Rab25 in ovarian cancer cells reduces the levels of BAX and BAK, and enhances the AKT phosphorylation, which in turn activates the phosphoinositide-3-kinase pathway." (PMID 25815277, 2015). "Induction of cisplatin-resistance via overexpression of Rab25 in the ovarian cancer cell line SKOV-3 has also been recently reported." (PMID 26384969, 2015). "High levels of Rab25 have been shown to correlate with poor prognosis and aggressiveness of ovarian cancers, so we initially looked at CLIC3 in patient samples from this disease." (PMID 22197222, 2012). "Prominently, the gene encoding ubiquitin B (UBB) shows a high correlation between methylation and expression in both data sets and RAB25 a known ovarian cancer suspect is also found in the TCGA data set." (PMID 22174824, 2011). "Combined with the results in ovarian cancer cells, it appears that manipulation of Rab25 levels can lead to aberrations in the trafficking of β1-integrin and perhaps other critical regulators of cell adhesion." (PMID 21063400, 2011). "Forced expression of Rab25 in ovarian cancer cells decreases levels of BAX and BAK and increases AKT phosphorylation, which in turn activates the phosphoinositide-3-kinase pathway." (PMID 21143914, 2010). "Mills and colleagues showed that 1q22 amplicon containing Rab25 is amplified in 50% of ovarian cancers." (PMID 21143914, 2010).
ovarian carcinoma (continued). "The expression of Rab25 correlated positively with AR expression supporting its role as an androgen responsive gene in ovarian cancer." (PMID 19623182, 2009). "It is possible that effects observed on Rab25 expression are mediated by an indirect mechanism, perhaps through TGFβ receptors, which have been shown to interact with the AR in ovarian cancer." (PMID 19623182, 2009). "Over-expression of RAB25 in both breast and ovarian cancer cells reportedly decreased apoptosis and increased proliferation of these cells in culture and increased their aggressiveness in vivo." (PMID 18822129, 2008). "Similarly, several Rab11a/Rab11b/Rab25 splicing isoforms are enriched in ovarian cancer compared to normal tissue." (PMID 35708998, 2022). "Rab25 promotes cancer in ovarian cancer by inhibiting autophagy." (PMID 34141705, 2021). "Meanwhile, in the analysis of ovarian cancer data from TCGA, NAMDD found 389 significant path associations, among which, we investigated and explained the disease pathogenesis mechanisms, including the CCNE1, AURKA, and RAB25 genes." (PMID 30944378, 2019). "The levels of Rab25 gene expression were significantly higher in stages III/IV ovarian cancers than in stages I/II tumors or normal ovary tissues, and elevated Rab25 expression was associated with a significantly worse survival rate in patients with ovarian cancer." (PMID 30791431, 2019). "Rab25 induces chemoresistance towards cisplatin, a first-line chemotherapeutic agent, commonly used in the treatment of patients with various types of cancer, such as advanced non-small cell lung cancer patients, metastatic breast cancer and ovarian cancer." (PMID 28969096, 2017). "Rab25 knockdown or Akt inhibitor was found to reduce cisplatin resistance in ovarian cancer cells." (PMID 28969096, 2017). "Indeed, Rab25 which interacts directly with RCP has been found to act as an oncogene in ovarian cancer and certain breast cancers and as a tumour suppressor in colon and intestinal carcinomas." (PMID 29285208, 2017). "On the contrary, ectopic overexpression of Rab25 in A2780 ovarian cancer cells increased cisplatin resistance in in vitro cell culture and in vivo i.p. tumor xenograft, indicating the functional role of Rab25 in inducing cisplatin resistance in conventional chemotherapy." (PMID 28969096, 2017). "Elevated expression of Rab25 decreased UV-induced apoptosis in ovarian cancer." (PMID 28969096, 2017). "Moreover, Rab25 down-regulation was reported to induce autophagic cell death in ovarian cancer from two independent research studies." (PMID 28969096, 2017). "Ectopic overexpression of Rab25 increased phospho-Akt level, which may mediate the cell proliferation-stimulating effect of Rab25 on ovarian cancer cells." (PMID 28969096, 2017). "Ovarian cancer patients with elevated RAB25 amplification either did not enter a disease free state following surgery and chemotherapy or showed very short disease-free survival, implicating RAB25 as potential driver gene correlated with poor prognosis and aggressive behavior of ovarian cancer." (PMID 28969096, 2017). "In 50% of ovarian cancers, 1q22 amplicon having Rab25 is amplified." (PMID 25815277, 2015). "Expression of Rab25, a member of the Ras superfamily of GTPases, in the ovarian cancer cell line A2780, allows these cells to invade and grow in the peritoneum of mice, resulting in tumour growth accumulation and death recapitulating the peritoneal disseminated disease in humans." (PMID 26384969, 2015). "When highly expressed in ovarian cancer cells, RAB25 facilitates invasion." (PMID 24216980, 2013). "Whether elevated Rab25 levels due to chromosome 1q amplification contributes to the elevated OPG levels in ascites of ovarian cancer patients remains to be determined." (PMID 25520884, 2013). "In breast and ovarian cancers, RAB25 may have a role as a tumor suppressor or an oncogene depending on the tumor subtype in which it is expressed." (PMID 24403269, 2013).